CXCL16 (C-X-C motif chemokine ligand 16)
Diseases named in the same sentence as CXCL16 in open-access papers (continued):
Sharing a sentence is not in itself a finding about the gene and the disease.
tumor (continued). "Upon intratumoral injection into multiple murine tumor models (A20, MC38, and EO771), the bacteria proliferated within the tumor and underwent density‐dependent lysis, releasing CXCL16^K42A and CCL20 to selectively recruit CD8+ T cells and precursor dendritic cells, respectively." (PMID 40878391, 2025). "To validate the hypothesis that tumor cells recruit Tc17 cells via the CXCL16-CXCR6 axis, we categorized spots with tumor cells into CXCL16+ and CXCL16- groups and compared the expression of CXCR6 in surrounding Tc17 cells." (PMID 40452847, 2025). "In clinical practice, such biomarkers could be readily assayed through plasma CXCL16 levels or tumor immunoblotting, guiding patient selection for combination therapy." (PMID 41375019, 2025). "Analysis of tumor clones revealed SCC‐specific COL6A1+/ITGA5+ carcinoma cells which produce CXCL16." (PMID 40776410, 2025). "CXCL16 facilitate tumor cell migration by interacting with its receptor CXCR6." (PMID 39995663, 2025). "Together, these studies indicate that local CXCL16 expression in tissues by stromal or tumor cells plays a critical role in TRM attraction and residency via CXCR6 and may compete to dictate where TRM precursors localize." (PMID 40862776, 2025). "Additionally, APOD+ myCAFs showed significant interactions with cytotoxic T and NK cells through the CXCL13 and CXCL16 signaling pathways, potentially contributing to tumor regression." (PMID 40107247, 2025). "The CXCR6/CXCL16 axis is crucial for TRM cell retention in tumours." (PMID 40361472, 2025). "Furthermore, circulating levels of exosomal miR-1246/92b-3p/27a-3p and CXCL16 were closely correlated with Fn abundance and tumor stage in CRC patients." (PMID 39000577, 2024). "Exosomes from Fn-infected CRC cells promote tumor metastasis by selectively carrying miR-1246/92b-3p/27a-3p and CXCL16, Fn promotes CRC metastasis by regulating KRT7-AS/KRT7, and Fn promotes CRC development by activating the cytochrome P450 and epoxyoctadecenoic acid axes." (PMID 38360615, 2024). "For example, CXCL16 facilitates tumor metastasis by modulating angiogenesis within the TME of CRC." (PMID 38962272, 2024). "Importantly, we demonstrated that CXCR6 was predominantly expressed in T and NK cells and played a pivotal role in mediating anti-tumor immunity through interactions with CXCL16+ macrophages and DC." (PMID 39588301, 2024). "Accordingly, while CXCL16+ tumor cells may trap T cells in the tumor mass, a tumor border composed by CXCL16+ glyCAF may, on the contrary, block T-cell migration and sequester the T cells in the tumor periphery." (PMID 38509063, 2024). "Moreover, in miR-29 overexpressing tumors, there were significant changes in cytokine and chemokine expression, such as upregulation of CCL5, CCL11, CXCL9, CXCL11, and CXCL16, known for their anti-tumor effects." (PMID 38890285, 2024). "Moreover, macrophages and DC1 cells within the tumor microenvironment secreted CXCL16, which recruited CXCR6+ CD8+ T cells and CXCR6+ NK cells to bolster anti-tumor responses." (PMID 39588301, 2024). "Although we focused on the CXCL16/CXCR6 axis as a potential mechanism for T cell blockade at tumor margins, proposing the disruption of this axis by blocking glycolysis in CXCL16+ glyCAF54,55, future studies may delve into more targeted interventions." (PMID 38509063, 2024). "Moreover, targeting CXCL16 either in cancer cells using shRNA or in the microenvironment using a neutralizing antibody efficiently blocks tumor growth and angiogenesis in thyroid cancers." (PMID 38172124, 2024). "Moreover, radiotherapy stimulates the release of chemokines such as CXCL9, CXCL10 and CXCL16 from tumor cells and stromal cells, which increase the infiltration of intratumoral NK, DC, and T cells, leading to enhanced anti-tumor immunity." (PMID 39712010, 2024). "Therefore, it becomes critical to consider the cellular sources of CXCL16 and their spatial positioning within the tumor mass." (PMID 38509063, 2024).
tumor (continued). "CXCL16 was upregulated in tumor cells in a melanoma mouse model after radiation therapy." (PMID 38928238, 2024). "Nanoparticles loaded with obeticholic acid were enriched in liver sinusoidal endothelial cells and Kupffer cells and attenuated tumor growth in an orthotopic mouse model, accompanied by increased secretion of CXCL16 and IFNγ and expansion of natural killer T (NKT) cell populations within the tumor." (PMID 37686465, 2023). "Interestingly, CXCL16 NAb injection significantly decreased the overall percentage of tumor-infiltrated CXCL16+ CD45.1+ cells in MCT-treated tumors." (PMID 37055410, 2023). "Since FOXQ1 and THBS2 were ectopically expressed in CC tumor cells it was of interest to compare their expression with other ectopically expressed biomarkers like the chemokines CXCL16 and CXCL17 particularly since these two chemokines were associated with bad prognosis." (PMID 38156105, 2023). "Because m6A participates in tumor-related drug resistance, we investigated whether CXCL16 helped regulate m6A methylation in OC cells." (PMID 37272931, 2023). "Accumulating evidence suggests that CXCL16 could be such a target because it affects tumor cell proliferation." (PMID 37272931, 2023). "In addition, IFNγ-driven increased expression of chemokines in tumors of Dox-treated mice, such as CCL2, CCL3, CCL5, and CXCL16 has been associated with enhanced recruitment of CD8+ T cells to tumors and reduced tumor progression." (PMID 37478172, 2023). "As a feedback loop, tumour cells secrete CXCL16 and CSF1 (colony-stimulating factor 1), both of which depend on the transcriptional activity of HIFs, leading to the recruitment of MSCs and macrophages to primary tumours and mediating the metastasis of tumour cells to lymph nodes and lungs." (PMID 35869057, 2022). "It is tempting to speculate that this chemokine–receptor pair could also regulate Treg migration and co-localization with cytotoxic CD8+ T cells in the tumour, on the basis of the expression of the ligand CXCL16 in DC3s." (PMID 35545675, 2022). "However, isolated tumor cells, even if cultured for 1-3 passages, had a substantial reduction in the CXCL16 expression levels." (PMID 36686729, 2022). "Besides, the CXCL16/CXCR6 pathway promotes tumor development and invasion, in different cell lines, such as mouse and human GBM cells." (PMID 35269652, 2022). "Moreover, a significant longer survival was observed in patients with high CXCL16 levels, suggesting its potential role as a prognostic biomarker, explained by a better improvement in the tumor-infiltrated lymphocytes (TILs) recruitment." (PMID 36429101, 2022). "Targeting MSCs and CXCL16/CXCR6 signalling to prevent the tumour recruitment of MSCs may be a novel effective therapeutic strategy for combating tumour metastasis." (PMID 35869057, 2022). "Expressed on CD8+ T, NK, and CD4+ T cells, CXCR6 could promote the recruitment of tumor-infiltrating lymphocytes in combination with CXCL16 expressed by tumor cells, thus contributing to a better prognosis for cancer patients." (PMID 35978426, 2022). "In the tumor setting, CD163+ tumor-associated macrophage, on the other hand, could elicit cancer associated fibroblasts (CAFs) to express CXCL16, which could further expand these fibroblasts in an autocrine manner." (PMID 36405734, 2022). "In intrahepatic inoculated fibrotic HCC mouse model, LSEC-targeted nano-delivery of simvastatin not only alleviates LSEC capillarization to regress the stromal microenvironment, but also recruits natural killer T (NKT) cells through CXCL16 to suppress tumor progression." (PMID 34983554, 2022). "We speculated that tumor-produced CXCL16 is a key retention molecule used to curb the residency of tumor-specific T cells in distant tissues." (PMID 33979626, 2021). "Transmembranous CXCL16 and soluble CXCL16 played opposite roles in tumor cell migration." (PMID 34805166, 2021). "We discuss the role of CXCL16 in tumor cell proliferation, migration, invasion, and metastasis." (PMID 33800554, 2021).
tumor (continued). "CXCL16 controls the accumulation of natural killer T cells and inhibits tumor growth." (PMID 35127816, 2021). "For, tumor CXCL16/CXCR6 axis might dominantly consume the large portion of CXCL16 and promote self-reproduction and migration, less CXCL16 would be released out to recruit the CXCR6+ T cells, which might be a distinct tumor escape mechanism in GC." (PMID 34345211, 2021). "These cells accumulate in a tumor where CXCL16 is up-regulated." (PMID 33800554, 2021). "We here mainly focused on the positive feedback of CXCL16 in tumor cell itself." (PMID 34345211, 2021). "Furthermore, the relative Cxcl16 expression level between the distant mucosa from tumor-bearing mice was comparable to that in the tumor-naive mucosa." (PMID 33979626, 2021). "Flow cytometry staining confirmed that 4T1 tumor cells can be a direct source of CXCL16 production." (PMID 33979626, 2021). "CXCL16 was one of genes that significantly upregulated in the tumor tissue." (PMID 34345211, 2021). "Interestingly, activation of the SDF-1 CXCR4 axis results in tumor mediated secretion of CXCL16 to recruit CXCR6 positive mesenchymal stem cells to the tumor microenvironment." (PMID 34503118, 2021). "It was hypothesized that once bound to mesothelin-overexpressing tumor cells, furin-mediated cleavage would release CXCL16 from the NRPbody and thereby recruit NK cells to the tumor sites." (PMID 33407739, 2021). "It remains to be determined how NRPbody will interact with a more complex and realistic immune contexture in the TME which consists of more than NK cells, as CXCL16 was shown in other tumor models to correlate with the infiltration of monocytes and M2-macrophages as well." (PMID 33407739, 2021). "CXCL16 expression was higher in GC tumor tissue compared to the adj-normal tissues (P<0.001)." (PMID 34345211, 2021). "Certain proinflammatory factors, such as CXCL9, CXCL10, and CXCL16, promote the trafficking of immune cells into the tumor, increase leukocyte chemoattraction and extravasation, and induce tumor surface expression of PD-L1, MHC-I, NK cell ligand, and Fas (CD95) [10,41,57,]." (PMID 34247198, 2021). "Then, the expression of CXCL16 is increased into the tumor microenvironment." (PMID 33800554, 2021). "Upregulation of CXCL16 in many cancers is related to its role as an inflammation marker, and inflammation in tumors creates a microenvironment enhancing further growth of a tumor." (PMID 33800554, 2021). "Compared to that in mucosal tissues, Cxcl16 expression in the tumor was significantly stronger." (PMID 33979626, 2021). "Furthermore, increased infiltration of CD8+ T cells expressing the chemokine receptor CXCR6—which is the receptor for CXCL16—was observed in the tumor tissues treated with iPS-ML-41BBL compared to those treated with iPS-ML." (PMID 33669419, 2021). "Although higher levels of TILs could be regarded as a favorable prognostic sign, the high expression of CXCL16 in tumor tissues accompanying increasing it self's expression of CXCR6 might effectively interrupted the antitumor immune process." (PMID 34345211, 2021). "Among these chemokines, CXCL16 has been showed as an important roles in the development of cancers, increasing of tumor infiltrating lymphocytes (TILs), regulating angiogenesis, controlling cell behaviors, and guiding migrating tumor cells to their targeted locations." (PMID 34345211, 2021). "Additionally, MDSCs in EC TME can be recruited and activated by cancer cell-derived cytokines/chemokines (IL-6, IGFBP-3, CXCL16, and GM-CSF), thereby accelerating tumor progression by inhibiting CD8+ T cell activation." (PMID 33995371, 2021). "In the current study, the secretion of interleukin-6 (IL-6), granulocyte colony-stimulating factor (GCSF) and chemokine (C-X-C motif) ligand 16 (CXCL16) was increased by the STK24-knockdown tumor cells in comparison to the secretion by the control-pEGFP tumor cells." (PMID 31892988, 2020).
tumor (continued). "For example, elevated concentrations of proteins (e.g. PAI-1, CXCL13 and CXCL16) in the blood could indicate YAP activation in HCC tumor cells, which is detectable in about 30% of all HCC cases." (PMID 33097058, 2020). "This, therefore, portrays the ability of CXCL16 to promote extravasation of migrating tumor cells." (PMID 32585812, 2020). "The combination treatment caused increased secretion of CCL2, CCL21, CXCL1, CXCL2, CXCL5, CXCL9 and CXCL16, whereas the levels of CCL11, CCL17, CCL19, CCL22, CCL25, CCL27 and CX3CL1, which are associated with protumourigenic effects, were decreased in the tumours." (PMID 33014356, 2020). "In GBM, CXCL16 may be an important factor in the modulation of microglia cell activity and their phenotype, as well as in the progression of the tumor." (PMID 32456359, 2020). "In addition to CORO1A, THBS1, PTP4A1, IL6, and CXCL16, the other nine genes were also upregulated in tumor tissues in TCGA." (PMID 32883954, 2020). "Finally, treatment of anti-CXCL16 blocking antibodies significantly inhibited the tumor growth of macrophage-laden PTCs in the murine model." (PMID 31527616, 2019). "Because CXCL16 is produced not only from cancer cells but also from various stromal cells including macrophages or fibroblasts, we then depleted it by using anti-CXCL16 neutralizing antibody in a macrophage-laden xenograft tumor model." (PMID 31527616, 2019). "CXCL16 mRNA analysis of lymph nodes was shown to give valuable prognostic information about patient survival in CC after curative surgery, either by itself or in combination with analysis of the tumor marker CEA mRNA." (PMID 31752131, 2019). "CXCL16 also acts as an important angiogenic factor in the tumor microenvironment." (PMID 31527616, 2019). "In conclusion, we observed increasing recruitment of VEGFR1+CD133+ HPCs to the lung during tumor metastasis and found high expression of CXCL-16, IL-2Rα, IL-2Rγ, MMP-1, MMP-9, PDGFR-α, SDF-1α, TGF-β, PECAM-1, and VE-cadherin in highly metastatic MDA-MB-435s cells." (PMID 30483898, 2019). "Furthermore, CXCL16 was expressed in bone metastasis, with weak staining detected in the lungs and liver metastasis, and was also correlated with tumor stage." (PMID 29642534, 2018). "Thus, the upregulation of such chemokines as CXCL-10 and CXCL-16 is important in the induction of CTL infiltration in the tumor due to radiation." (PMID 30487462, 2018). "The upregulation of CXCL-16 by the tumor and the induction of TILs improve survival in mice." (PMID 30487462, 2018). "To confirm a role of CXCL16 in driving GAMs toward a pro-tumor phenotype in vivo, we implanted GL261 cells into the brain of wt and cxcr6ko mice and, after 17 days, CD11b+ cells were isolated from the ipsi- and contra-lateral brain hemispheres of each mice and analyzed by RT-qPCR." (PMID 30542347, 2018). "Our results on CXCL16 in UC tissue, together with those from previously published data in other solid tumours suggest a critical role for this chemokine in tumour progression, patient prognosis, and as a potentially successful treatment by targeted immunotherapy." (PMID 29285224, 2017). "As a consequence, we lack pre-diagnostic samples from cases and may therefore overestimate the CXCL16 concentrations in cases that already have clinical symptoms due to a larger tumour." (PMID 29285224, 2017). "Numerous studies have demonstrated that RT leads to increased local production of soluble factors that promote anti-tumor immunity by enhancing activation of local innate immune cells and recruitment of tumor-reactive T cells (e.g., CXCL16, IL-1α/β, IFNγ, and TNFα)." (PMID 28134800, 2017). "Similarly, adoptive transfer of glycolipid-loaded CXCL16+/+ BMDCs mediated enhanced protection from tumor metastasis compared to CXCL16−/− BMDCs." (PMID 27471636, 2016). "Interestingly, treatment of tumor-bearing mice with CXCL16−/− DCs induced higher levels of serum alanine aminotransferase (ALT) compared to CXCL16+/+ DCs." (PMID 27471636, 2016).
tumor (continued). "Interestingly, the expression of CCL20 and CXCL16 by tumor cells has been reported to be correlated with prognosis and infiltration of lymphocytes into cancer tissues." (PMID 27517754, 2016). "Moreover, CXCL16, a chemoattractant for CXCR6 expressing tumor cells, has been linked to an increase in tumor cell migration and invasion in prostate cancer and pancreatic ductal adenocarcinoma (PDAC)." (PMID 27618112, 2016). "Taken together, these studies suggest that transmembrane CXCL16 may promote antitumor responses whereas soluble CXCL16 may contribute to tumor progression." (PMID 27471636, 2016). "Given the high frequency of iNKT cells in the liver relative to other tissues, we wanted to determine whether CXCL16+/+ DCs could enhance tumor control at other sites." (PMID 27471636, 2016). "Furthermore, glycolipid-loaded CXCL16hi or CXCL16+/+ DCs provided enhanced protection from tumor metastasis compared to CXCL16neg or CXCL16−/− DCs." (PMID 27471636, 2016). "We next evaluated the levels of secreted CXCL16 using an enzyme-linked immunosorbent assay (ELISA) on supernatants from primary CAFs and showed that CAFs isolated from TN tumours (3/4) secreted high amounts of CXCL16, while low CXCL16 was measured in CAFs isolated from ER+ tumours (0/8)." (PMID 27725631, 2016). "IR also has the ability to induce the production and release of CXCL16 in tumor cells." (PMID 26500646, 2015). "Moreover, CXCL16 also indirectly induces the infiltration of M1 macrophages, which induce tumor cell apoptosis by secreting TNF-α." (PMID 25495942, 2014). "Our studies have confirmed the expression of CXCL16 in various cancer cell lines and tumor tissues, indicating that CXCL16 might serve as a useful biomarker for various types of cancer." (PMID 25495942, 2014). "The protein CXCL16 (CXC motif ligand 16) is released from irradiated tumor." (PMID 23233905, 2012). "Previous studies showed that RT upregulated the expression of VCAM-1 on the tumor vasculature and induced the release of chemokines, such as CXCL16 from tumor cells, which may favor the trafficking of immune effector cells to the tumor tissue." (PMID 22666458, 2012). "Moreover, radiation was shown to recruit lymphocytes to carcinomas through the release of CXCL16 by tumour cells." (PMID 20664601, 2010). "CXCL16 could enhance tumor growth directly through CXCR6-mediated effects on the proliferation/survival of cancer cells and indirectly through enhanced recruitment and proliferation/survival of cytokine-producing T cells." (PMID 19690611, 2009). "Notably, CXCL16 (a ligand) from tumor cells and CXCR6 (a receptor) on HLA-DR+CD38+CD8+ T cells—previously implicated in enhancing anti-PD-1 therapy efficacy in other cancers—may mediate key tumor‒immune interactions." (PMID 41565617, 2026). "Additionally, CXCL16 or CXCR6 signaling can directly support tumor progression and invasion." (PMID 41157253, 2025). "Additionally, in hepatocellular carcinoma, Piezo1 may be involved in tumor-associated angiogenesis driven by matrix stiffness by upregulating VEGF, CXCL16, and IGFBP2." (PMID 41226585, 2025). "Like with CXCL16 blockade, TGF-β neutralization has also been demonstrated to cause downregulation of tissue residency markers, leading to enhanced systemic tumor immunity, secondary tumor response, and overall survival when combined with PD-L1 blockade in mice." (PMID 40862776, 2025). "Interestingly, high intratumoral expression of CXCR6 is not primarily driven by chemotactic gradients involving its ligand CXCL16 but rather is upregulated locally by the tumor microenvironment itself, indicating an intrinsic regulatory mechanism within the tumor milieu." (PMID 41149503, 2025). "However, there were also elevated cytokines from the Beads-FT-mA20T that could potentially contribute to the tumour-promoting responses, as represented by increased levels of CXCL16, CXCL2 and CCL17 (See Section 4)." (PMID 40361460, 2025).